TAS1R2 (taste 1 receptor member 2)
Description:
Putative taste receptor. TAS1R2/TAS1R3 recognizes diverse natural and synthetic sweeteners.
Synonyms: GPR71; T1R2; TR2
Tractability: Small molecule: it belongs to a druggable protein family. Antibody: its Gene Ontology location is reachable by antibodies, with high confidence; UniProt places it where antibodies can reach, with medium confidence; UniProt predicts a signal peptide or a membrane-spanning region. PROTAC: a small molecule that binds it is known.
Target class: Membrane receptor; Taste receptor (family C GPCR); Family C G protein-coupled receptor
Gene: Protein-coding gene on chromosome 1 (18,839,599 to 18,859,660, reverse strand). Ensembl gene ENSG00000179002.
Subcellular location: Cell membrane
Pathways (Reactome):
Signal Transduction: Class C/3 (Metabotropic glutamate/pheromone receptors); G alpha (i) signalling events
Sensory Perception: Sensory perception of sweet, bitter, and umami (glutamate) taste
Gene Ontology:
Molecular function: protein binding; sweet taste receptor activity; taste receptor activity; G protein-coupled receptor activity
Biological process: detection of chemical stimulus involved in sensory perception of sweet taste; positive regulation of cytokinesis; sensory perception of sweet taste; G protein-coupled receptor signaling pathway; sensory perception of taste
Cellular component: G protein-coupled receptor dimeric complex; receptor complex; sweet taste receptor complex; membrane; plasma membrane
Genetic constraint (gnomAD): Loss-of-function variants: 48 observed, 54.19 expected, observed/expected ratio (o/e) 0.89, 90% interval 0.7 to 1.13. The upper end of that interval is the gene's LOEUF score, 1.13, which puts it in group 4 of 6, group 1 being the genes least tolerant of losing a copy. Missense variants: 1,155 observed, 1,175.6 expected, observed/expected ratio (o/e) 0.98, 90% interval 0.94 to 1.03. Synonymous variants: 479 observed, 490 expected, observed/expected ratio (o/e) 0.98, 90% interval 0.91 to 1.05.
Homologues: Orthologues: chimpanzee TAS1R2 (99% identical), macaque TAS1R2 (92% identical), dog TAS1R2 (76% identical), pig TAS1R2 (76% identical), rat Tas1r2 (71% identical), guinea pig TAS1R2 (71% identical), mouse Tas1r2 (70% identical), rabbit TAS1R2 (64% identical), zebrafish tas1r2.2 (33% identical), zebrafish tas1r2.1 (32% identical). Paralogues in human: TAS1R1 (36% identical), CASR (30% identical), TAS1R3 (28% identical), GPRC6A (28% identical).
Diseases named in the same sentence as TAS1R2 in open-access papers:
TAS1R2 is named in the same sentence as 25 diseases in open-access papers, as found by Europe PMC text mining. Sharing a sentence is not in itself a finding about the gene and the disease. The quoted sentences say what the papers report.
Obesity (13 papers, 2014 to 2025). Accumulation of substantial excess body fat. "Strikingly, Tas1r2 knockout animals are partially protected from metabolic disturbances associated with diet-induced obesity, including hyperinsulinemia." (PMID 38691547, 2024). "Thus, we used participants with variable glycemic profiles and obesity to assess the effects of the TAS1R2-Ile191Val variant." (PMID 35662939, 2022). "Even though TAS1R3 and GNAT3 were not related to sweet perception in this review, a third sweet-related gene, TAS1R2, has been observed to be linked with sweet taste threshold and consumption of sweet food in individuals with obesity compared to individuals with normal weight." (PMID 32635385, 2020). "We therefore investigated associations between TAS1R2 and TAS2R38 variants, SSB intake, and obesity risk in Kuwaiti adolescents, aiming to contribute to the growing field of nutrigenetics and to inform future personalized nutrition interventions." (PMID 41007057, 2025). "This study explored the associations between genetic variants in taste receptor genes, specifically TAS1R2 and TAS2R38, with obesity risk and SSB consumption among Kuwaiti adolescents." (PMID 41007057, 2025). "This study examined associations between TAS1R2 and TAS2R38 polymorphisms, sugar-sweetened beverage (SSB) intake, and obesity risk in Kuwaiti adolescents." (PMID 41007057, 2025). "This in vitro study aims to measure the impact of human TAS1R2/TAS1R3 polymorphisms, some of which are thought to be involved in obesity, on the response of the sweet taste receptor to various sweeteners." (PMID 40289963, 2025). "Our focus on TAS1R2 and TAS2R38 provides insight into culturally relevant dietary behaviors and the heightened obesity risk among adolescents in Kuwait, a region that remains underrepresented in nutrigenomics research." (PMID 41007057, 2025). "Genetic variations in taste receptor genes, particularly TAS1R2 and TAS2R38, may influence taste preferences, dietary intake, and obesity risk." (PMID 41007057, 2025). "In Kuwait, where obesity prevalence is among the highest globally, no prior studies have investigated TAS1R2 and TAS2R38 variants in relation to SSB consumption in adolescents." (PMID 41007057, 2025). "Background/Objectives: Studies have hypothesised that single-nucleotide polymorphisms (SNPs) in the TAS1R2 and TAS1R3 genes may alter sweet compound detection and eating habits, thereby increasing the risk of obesity." (PMID 40289963, 2025). "It would also be possible to verify whether there are sensory and nutritional intake differences between mutation carriers of the TAS1R2 gene and the TAS1R3 gene to determine whether one of these genes is predominantly involved in obesity." (PMID 40289963, 2025). "Finally, our data suggested that factors other than the TAS1R2 and TAS1R3 SNPs were associated with obesity." (PMID 40289963, 2025). "Variants in TAS1R2 and TAS1R3 sweet taste receptor genes have previously been associated with changes in taste sensitivity to sugar, the excessive consumption of which is an established risk factor for obesity and chronic disease." (PMID 30060620, 2018). "Evaluated genotypes also included those relating to cardiovascular health (ACE), obesity and metabolism-related genotypes (FTO, UCP1, MC4R, and ADIPOQ), sweet taste perception (Tas1R2 and KCTD10), and endurance (GDF5)." (PMID 36235756, 2022). "Our results did not necessarily show a clear link between certain human phenotypes (higher sugar intake and/or higher sweet detection threshold) and the cellular response of associated SNPs, suggesting that TAS1R2 and TAS1R3 SNPs are probably not the only factors associated with obesity." (PMID 40289963, 2025).
dental caries (7 papers, 2018 to 2026). The decay of a tooth, in which it becomes softened, discolored, and/or porous. "A candidate gene study found that the taste receptor genes, TAS2R38 (bitter) and TAS1R2 (sweet), were associated with dental caries in primary and mixed dentition, respectively, in the COHRA1 cohort, one of the five cohorts included in this study." (PMID 36672800, 2022). "The rs35874116 single nucleotide polymorphism (SNP) in the sweet receptor gene TAS1R2 has been associated with dental caries at a high risk in permanent teeth among school children and adults." (PMID 36335309, 2022). "In a small study investigating multiple genotypes, allelic variation in sweet taste genes, including GNAT3, SLC2A2, SLC2A4, TAS1R1 and TAS1R2 was associated with dental caries." (PMID 34715836, 2021). "Two genes, namely, taste 2 receptor member 38 (TAS2R38) and taste 1 receptor member (TAS1R2), have been identified to be important in taste sensing and to be associated with dental caries risk and/or protection." (PMID 29849633, 2018). "In preschool-aged children, SNP variants in TAS1R2 have beenassociated with dietary sugar intake and SNP variants in GNAT3 have beennominally associated with dental caries." (PMID 39076398, 2023). "The present study provides evidence for gene variation of rs35874116 within TAS1R2, which is related to both sweet consumption frequency and dental caries." (PMID 36335309, 2022). "Several previous studies have identified an association between several genes and dental caries, including genes related to enamel formation such as AMBN, AMELX, and ENAM; taste receptor genes such as TAS2R38, TAS1R2; immune-related genes such as HLA; and saliva genes such as MUC5B, PRH1." (PMID 38414691, 2024). "Likewise, sweet taste sensitivity and liking associated with polymorphisms present in TAS1R2 and GLUT2 sweet taste genes have also been related to the higher prevalence of dental caries." (PMID 34715836, 2021).
diabetes (4 papers, 2017 to 2025). "Incorporating a nutrigenetic approach—such as investigating the role of TAS1R2 polymorphisms in sweet taste perception and their relationship with dietary behavior and diabetes susceptibility—could further enhance the clinical relevance of our results and potentially improve patient compliance." (PMID 40806099, 2025). "In total, 3,602 participants (46–68 years old) from the MDC cohort who underwent baseline examinations between 1991 and 1994, who were non-smokers without diabetes, and for whom information regarding TAS1R2 rs7534618 (a proxy for rs12033832) was available were included in this study." (PMID 29326656, 2017).
Hyperglycemia (2 papers, 2018 to 2022). An increased concentration of glucose in the blood. "Because the rate of glucose excursions can affect the duration and magnitude of postprandial hyperglycemia, we explored contributions of TAS1R2-(Ile191Val) at baseline and during an OGTT or an FSIVGTT in a cohort of adults with various degrees of glucose control." (PMID 35662939, 2022).
Hyperinsulinemia (2 papers, 2019 to 2024). An increased concentration of insulin in the blood. "When fed an obesogenic diet, TAS1R2 knockout animals are partially protected against weight gain, fat mass gain, and hyperinsulinemia." (PMID 38691547, 2024).
Chronic colitis (1 paper, 2023). A chronic inflammatory disease of the large intestine (colon, cecum and rectum). "Chronic colitis reduced sweet taste transmission to the brain, in parallel with the downregulation of the Tas1r2 sweet receptor subunit in oral taste receptor cells." (PMID 37919307, 2023).
fatty liver (1 paper, 2019). "Besides the genes related to fatty liver, these findings may be linked to the ancestral Amerindian-derived risk alleles of the taste receptors TAS1R2, CD36, and TAS2R38 that are known to alter food preferences." (PMID 30608932, 2019).
lung squamous cell carcinomas (1 paper, 2022). "TAS1R2 was mutated in roughly 5% of lung, colon, and stomach adenocarcinomas and TAS2R60 was mutated in ~ 4% of lung squamous cell carcinomas." (PMID 35624283, 2022).
lupus erythematosus (1 paper, 2025). An autoimmune, connective tissue chronic inflammatory disorder affecting the skin, joints, kidneys, lungs, heart, and the peripheral blood cells. "The animal experiment found that the mice with lupus erythematosus had a reduced preference for sucrose along with significantly increased serum levels of IL-6 and interferon-γ, and downregulating Tas1r2 was observed in the mice with chronic colitis disease." (PMID 40090940, 2025).
pancreatic cancer (1 paper, 2022). "A recent study of 2,854 SNPs in 50 taste-related genes reported association of a taste 1 receptor member 2 (TAS1R2)- rs11261087 variant with pancreatic cancer risk." (PMID 35903357, 2022).
cancer (2 papers, 2017 to 2024). A tumor composed of atypical neoplastic, often pleomorphic cells that invade other tissues. "The aim of the present study was to examine the association between dietary intake and the TAS1R2 genotype in lean and overweight individuals in the population-based Malmö Diet and Cancer (MDC) cohort using dietary intake data with a high validity." (PMID 29326656, 2017). "The purpose of this study was to examine the relationship between the SNP rs12033832 in TAS1R2 and dietary intake in a larger, older, population-based cohort, i.e., the Malmo Diet and Cancer Study cohort." (PMID 29326656, 2017).
metabolic disease (1 paper, 2025). A congenital disorder (due to inherited enzyme abnormality) or acquired (due to failure of a metabolically important organ) disorder resulting from an abnormal metabolic process. "Our findings establish TAS1R2 as a metabolic regulator in skeletal muscle and highlight the utility of genetically diverse mouse populations in dissecting gene-diet interactions relevant to human metabolic diseases." (PMID 40507187, 2025).
tumor (1 paper, 2022). "Across all tumor types, the median percentage of tumors with nonsilent mutations in TAS1Rs, including TAS1R1, TAS1R2, TAS1R3, was slightly less than 1%." (PMID 35624283, 2022).
TAS1R2 also shares sentences with these, for which no sentence is quoted: type 2 diabetes (3 papers); hypertriglyceridemia (2); connective tissue disorder (1); COVID-19 (1); eosinophilia (1); Glucose intolerance (1); metabolic syndrome (1); morbid obesity (1); nonalcoholic fatty liver disease (1); skin melanoma (1); stomach adenocarcinomas (1); viral infections (1).